MT-ATP6 (mitochondrially encoded ATP synthase membrane subunit 6)
Diseases named in the same sentence as MT-ATP6 in open-access papers (continued):
Sharing a sentence is not in itself a finding about the gene and the disease.
urea cycle disorder (1 paper, 2023). A genetic inborn error of metabolism characterized by the deficiency of one of the enzymes necessary for the urea cycle. "Even at newborn screening (and after excluding urea cycle disorders), low citrulline is suggestive of MT-ATP6 mutations 8993T>G/C and m.9176T>C/G." (PMID 37628588, 2023).
tumor (23 papers, 2012 to 2026). "By using a yeast model organism, it was shown that the mutation mt-ATP6-P136S specifically found in PCa tissues positively correlates with tumor progression and may be involved in cancer cell escape from apoptosis." (PMID 36831534, 2023). "Particularly, at the single-site level, three CpG positions were significantly hypermethylated in tumors relative to matched non-tumor samples, two located within MT-ATP6 gene and one in the short intergenic region between MT-ND2 and MT-CO1 genes." (PMID 41602822, 2026). "Moreover, immunohistochemistry (IHC) analysis showed markedly reduced staining for mitochondrial ATP synthase (MT-ATP6) expression in VC-treated mouse tumor tissues compared to control tumor tissues, consistent with our in vitro results." (PMID 39083898, 2024). "Interestingly, one of the tumour samples (T10) had several mutations in mtDNA: MT‐ND1, MT‐ND4 and MT‐ATP6." (PMID 37317665, 2023). "The introduction of pathogenic m.8993T>G and m.9176T>C point mutations in the MT‐ATP6 gene in to EB8 HeLa‐derived cell lines increased cell proliferation in culture and led to a greater expansion of tumour cells in xenografts, which was suppressed by the restoration of wild‐type MT‐ATP6." (PMID 35842901, 2022). "Furthermore, tenofovir's negative effect on mitochondrial function could lead to impairment of tumor progenitor cell apoptosis, as has been specifically reported for loss-of-function mutations of mtATP6, a mitochondrial gene strongly suppressed by tenofovir in our study." (PMID 25647729, 2015).
cancer (15 papers, 2008 to 2026). A tumor composed of atypical neoplastic, often pleomorphic cells that invade other tissues. "Pan-cancer survival analyses further confirmed the clinical relevance of elevated MT-ATP6 activity, which was associated with inferior chemotherapy outcomes." (PMID 41727571, 2026). "Several mutations within the MT-ATP6 gene have been found in different human carcinomas, promoting tumor growth by reducing cell death." (PMID 36674816, 2023). "In addition, several mt-ATP6 mutations have been detected in different human cancer cell lines and solid tumors, next to the 8414 position and affecting aH5 helix." (PMID 36674816, 2023). "Indeed, some carcinomas present MT-ATP6 mutations while others downregulate the expression of the catalytic subunit β-F1-ATPase reducing in that way OXPHOS activity to favor the metabolic switch to a Warburg phenotype that promotes growth and cell survival." (PMID 36674816, 2023). "In addition, six transcripts (MT-ATP6, MT-CO1, MT-CYB, MT-ND1, MT-ND6, and MT-RNR1) were quantified in 62 cancer tissues by real-time RT-PCR." (PMID 18842121, 2008).
mitochondrial disease (8 papers, 2011 to 2025). "The heterogeneity of mitochondrial disease was demonstrated by confronting the clinical and biochemical data of two patients with the uncommon pathogenic homoplasmic NC_012920.1(MT-ATP6):m.9035T>C variant." (PMID 35159298, 2022). "The first mitochondrial disease caused by an ATP synthase dysfunction was found in patients with mutations in MT-ATP6, a mitochondrial gene encoding a key component of the Fo proton channel." (PMID 33238568, 2020). "The m.T8993G pathogenic mutation in MT-ATP6 was the first reported mitochondrial disease associated with an ATP synthase defect." (PMID 33238568, 2020). "There are several diagnostic caveats associated with MT‐ATP6–related mitochondrial disease compared to other common mtDNA mutations." (PMID 31187502, 2019). "RP was most prevalent in m.8993T>G‐related mitochondrial disease compared to other MT‐ATP6 variants; however, RP was only clinically identified in less than a third of all patients." (PMID 31187502, 2019). "Five lymphoblastoid cell lines derived from mitochondrial disease patients harboring point mutations in mtND1, mtND4, or mtATP6 were characterized in two high throughput assays assessing mitochondrial function." (PMID 29587845, 2018). "To elucidate the genotype–phenotype correlate of MT‐ATP6–related mitochondrial disease and associations with the underlying mutations, we sought to characterize MT‐ATP6–associated mitochondrial disease in a well‐characterized, large mitochondrial disease patient cohort." (PMID 31187502, 2019).
infection (6 papers, 2006 to 2025). The state of being infected such as from the introduction of a foreign agent such as serum, vaccine, antigenic substance or organism. "Thus, assessing the exact expression of particular genes, such as mt-ND1, mt-CO1, and mt-ATP6, might serve as a more precious role in determining related clinical outcomes of infection." (PMID 39113822, 2024).
brain disorder (1 paper, 2023). A disease affecting the brain or part of the brain. "Mitochondrial dysfunction has long been implicated in the pathogenesis of PD, and several studies have identified mutations in mt-Co2, mt-Co2, mt-Co3, and mt-Atp6 associated with various clinical brain disorders." (PMID 38041169, 2023).
Kidney (1 paper, 2022). "The amino acid change associations were previously predicted between Prost-AdenoCA and MT-ND5 (13789 T > C, Y485H), Kidney-RCC and MT-ND6 (14178 T > C, I166V), and Kidney-ChRCC and MT-ATP6 (8584 G > A, A20T)." (PMID 35183124, 2022).
MT-ATP6 also shares sentences with these, for which no sentence is quoted: retinitis pigmentosa (21 papers); peripheral neuropathy (5); prostate carcinoma (5); sterility (4); cyst (3); diabetes (3); Encephalopathy (3); hypertrophic cardiomyopathy (3); infertile (3); retinitis pigmentosa syndrome (3); Alzheimer disease (2); cardiovascular diseases (2); cerebellar ataxia (2); coronary artery disease (2); Huntington disease (2); Hypertension (2); microcephaly (2); neurodevelopmental disorder (2); open-angle glaucoma (2); optic atrophy (2); Parkinsonism (2); primary open angle glaucoma (2); retinopathy (2); Adult onset (1); Alpers syndrome (1); asthenozoospermia (1); basal ganglia disease (1); brain tumours (1); Cerebellar atrophy (1); coenzyme Q10 deficiency (1).
A further 66 diseases each share a sentence with MT-ATP6 in 1 paper.